FGFR2 (fibroblast growth factor receptor 2)
Diseases named in the same sentence as FGFR2 in open-access papers (continued):
Sharing a sentence is not in itself a finding about the gene and the disease.
bladder cancer (55 papers, 2010 to 2026). "Both NCCN and European Society for Medical Oncology (ESMO) guidelines recommend the detection of FGFR2/3 mutations and fusions in bladder cancer, and the FDA has also approved the therascreen® FGFR RGQ RT-PCR kit as a PCR-based companion diagnostic kit." (PMID 38831455, 2024). "The pan-FGFR inhibitor erdafitinib has shown an overall response rate of 40% in bladder cancer patients whose tumors contained FGFR3 point mutations or FGFR2/3 fusions, leading to FDA approval of this drug in locally advanced or metastatic bladder cancer." (PMID 39031286, 2024). "Erdafitinib targets the fibroblast growth factor receptor 2/3–activating (FGFR2/3-activating) mutations or fusions that occur in less than 20% of advanced bladder cancer." (PMID 35852858, 2022). "FGFR1 amplification has been identified in 10–20% of patients with non-small cell lung cancer whereas 4–10% of primary gastric cancers and approximately 75% of bladder cancers harbor FGFR2 amplification and FGFR3 mutations, respectively." (PMID 33898310, 2021). "The presence of TIL is positively correlated to overall survival in bladder cancer and inversely correlated to FGFR2/3‐mutated genetic status." (PMID 34114376, 2021). "For example, FGFR2 loss of function mutations have been reported in 10% of melanoma tumors and cell lines as well as in bladder cancers." (PMID 34068954, 2021). "Erdafitinib was the only pan-FGFR inhibitor approved by the FDA (2019) for bladder cancer patients with FGFR2/3 mutations." (PMID 32325639, 2020). "On the obverse, down-regulation of FGFR2 in bladder cancers was associated with an adverse prognosis." (PMID 27154171, 2016). "FGFR2/3 mutations or fusions were evidently more frequent in upper tract UCs than in bladder carcinomas (10/21 (48%) vs. 30/147 (20%), p = 0.012), and in patients with localized disease compared to subjects with advanced or metastatic disease (29/99 (29%) vs. 16/9 9 (16%); p = 0.041)." (PMID 39596194, 2024). "However, the first targeted agent for bladder cancer, erdafitinib, is active and is approved to treat postplatinum patients with activating somatic FGFR2/3 mutations or fusions, which are seen in approximately 15% of patients." (PMID 35852858, 2022). "However, the clinical outcome of these treatments strictly relies on the presence of an elevated immune signature or FGFR2/3 specific mutation (typical of patients with a luminal I bladder cancer subtype)." (PMID 35480108, 2022). "Methylation-induced transcriptional FGFR2 downregulation is thus associated with poorer prognosis in hepatocellular carcinoma and bladder cancer, analogous to functional losses caused by FGFR2 deletion in glioblastomas, or loss of FGFR2 heterozygosity in osteosarcomas." (PMID 34007277, 2021). "Interestingly, serine 780 in FGFR2 has been found mutated to leucine in a patient with bladder cancer." (PMID 31146385, 2019). "It was further observed that EGF and CDH1 in the PPI network were annotated as being bladder cancer-associated proteins, and both receptor FGFR2 and PDGFRB could interact with EGF." (PMID 24801713, 2014).
bladder cancer (continued). "Ongoing efforts in bladder cancer have yielded significant improvements in the care of patients, especially in the metastatic setting, through FGFR2/3 targeting, as well as with immunotherapy options with PD-L1 inhibitors." (PMID 37240925, 2023). "FGFR2 amplification has also been found in other tumors, such as gastric, esophageal, squamous cell lung, liver, and bladder cancers." (PMID 37783677, 2023). "Results from phase I and II trials of BGJ398 and erdafitinib in this population reported response rates of 25–40%, and based on these findings, erdafitinib was FDA approved for FGFR2/3 aberrant bladder cancers in 2019." (PMID 35501832, 2022). "Specifically in bladder cancer, these FDA‐approved, companion diagnostic biomarkers are FGFR3 mutation and FGFR2/3 fusion." (PMID 34114376, 2021). "We showed that a computationally derived imaging biomarker for TIL presence, TIL percentage, can predict FGFR2/3 mutation and, more broadly, FGFR activating mutation in bladder cancer." (PMID 34114376, 2021). "Our modeling also predicted opposing roles for FGF signaling in the bladder and uterine cancers: where FGFR2 exerts a tumor-suppressor effect in bladder cancer yet a tumorigenic effect in uterine cancer." (PMID 34408236, 2021). "The first is erdafitinib, which is licensed for patients with advanced bladder cancers expressing either FGFR3 or FGFR2 aberrations." (PMID 34007277, 2021). "It has been reported in the literature that silencing circular RNA UVRAG (also known as Hsa_circ_0023642) inhibited bladder cancer growth and metastasis by targeting the miR‐223/FGFR2 axis." (PMID 32562304, 2020). "It has been reported that reduction of FGFR2b levels in urothelial cancer samples correlate with decreased survival and the chromosomal arm 10q, where the FGFR2 gene is located, is often lost in advanced bladder cancer." (PMID 31146385, 2019). "The enhancement of the FGFR2 pathway would lead to urothelium proliferation and FGFR1, as well as FGFR3 gene amplification can cause urinary bladder carcinoma." (PMID 31878098, 2019). "A switch from FGFR2-IIIb to FGFR2-IIIc has been reported in the malignant progression of prostate and bladder cancer." (PMID 27677589, 2016). "Paradoxically, wildtype FGFR2-IIIb has been described as a tumor suppressor in pre-clinical systems of bladder cancer and prostate cancer." (PMID 24550739, 2014). "In other tumors, FGFR2 has been suggested to exert tumor suppressor activity, as it happens in thyroid, prostate and bladder cancers." (PMID 24899248, 2014). "Switching of FGFR expression to the IIIc isotypes has been shown for FGFR2 and FGFR1, and was described to be associated with tumour progression in prostate and bladder cancer." (PMID 20234367, 2010). "The remaining four genes, CRTC1, MB21D2, USP44 and FGFR2, may drive bladder cancer through other mechanisms of pathway crosstalk, which requires further investigation." (PMID 40768543, 2025). "However, to date, for patients with advanced or metastatic bladder cancer and alterations in the FGFR2 or FGFR3 gene, targeted therapy based on the inhibitor of FGFR (erdafitinib) is available." (PMID 39768623, 2024). "Moreover, another study showed that a reduction in ESRP1 or ESRP2 promoted bladder cancer cell growth and lung metastasis by altering FGFR2 splicing and macrophage polarization." (PMID 39132499, 2024). "In bladder cancer, ESMO guidelines recommend NGS for FGFR2/3 mutation and fusion detection." (PMID 38831455, 2024). "Utilizing a histologically derived metric, TIL percentage, we were able to generate a predictive tool that could confidently screen for FGFR2/3 gene mutation, as well as other FGFR aberrations, in a large population of bladder cancer patients." (PMID 34114376, 2021). "Truncated forms of FGFR2 lacking the C-terminal tail, including S780, have been identified in cancer and S780 has been found mutated to leucine in bladder cancer." (PMID 31146385, 2019).
bladder cancer (continued). "It is possible that FGFR2 plays a tumor-suppressing role in earlier stages of bladder cancer, but could have tumor-promoting effects in certain patients with advanced bladder cancer." (PMID 31146385, 2019). "Although increased signaling and increased migration are traits that normally would benefit cancer cells, the role of FGFR2 signaling in bladder cancer is not fully understood and the FGFR2b isoform has been suggested to act as a tumor suppressor in the urothelium." (PMID 31146385, 2019). "In particular, FGFR2-IIIc expression has been correlated to epithelial to mesenchymal (EMT) transition of tumor cells in bladder cancer, which may represent a key factor in tumor progression by increasing the metastatic potential of cancer cells." (PMID 24899248, 2014). "However, FGFR-2-IIIb isoform re-expression in prostate and bladder cancer cell lines resulted in growth suppression in vitro and in decreased tumor formation in vivo." (PMID 23977259, 2013). "In rat prostate and bladder cancer models it has been indicated a switch from FGFR-2-IIIb to FGFR-2-IIIc isoform, which might contribute to alter the balance between epithelial and mesenchymal cells and to promote epithelial-mesenchymal transition." (PMID 23977259, 2013). "As amplification/overexpression of FGFR1, FGFR2, and FGFR3 contributes to progression of lung, gastric, and bladder cancers, respectively, we verified their level of expression in all analyzed cell lines." (PMID 33898310, 2021). "In prostate and bladder cancers, the expression of FGFR2IIIc, another splicing isoform of FGFR2, correlated with more malignant phenotype, compared with KGFR." (PMID 22159401, 2012). "For example, the database BoostDM only covers FGFR3 based on mutational data from bladder cancer and provides no information at all for FGFR1, FGFR2 or FGFR4." (PMID 41361008, 2026). "Our findings are consistent with the results of the TCGA data set for the “squamous-like” subtype of bladder cancer (n = 85), which revealed reduced overall expression of FGFR1 and FGFR2 in tumors compared to normal tissue, while expression of FGFR3 remained high." (PMID 27669755, 2016). "However, no studies have addressed the FGFR2 splicing regulation of hnRNP-F, hnRNP-H, and hnRNP-M in bladder cancer." (PMID 39132499, 2024). "Moreover, PDGFRB rather than FGFR2 could form a heterodimer with EGFR on bladder cancer cells, and this could induce resistance to anti-EGFR therapy for bladder cancer." (PMID 24801713, 2014).
colorectal cancer (47 papers, 2010 to 2026). A primary or metastatic malignant neoplasm that affects the colon or rectum. "In contrast, A648T was frequently identified in 23% (9 of 38 cases) of colorectal cancer with FGFR2 mutations." (PMID 41226813, 2025). "FGFR2 gene amplification resulting in FGFR2 overexpression and constitutive activation is also associated with colorectal cancers." (PMID 29420662, 2018). "Similarly, activating mutations in the fibroblast growth factor receptor 2 (FGFR2) in colorectal cancer activate PD-L1 expression via the JAK/STAT3 pathway." (PMID 32992658, 2020). "Amplification of the FGFR2 gene is also associated with colorectal cancers." (PMID 29420662, 2018). "For example, we used stat-FISH to investigate H716, a colorectal cancer cell line where interSeg predicted EC-amp for two distinct probes, corresponding to FGFR2 and MYC, for each investigated cell." (PMID 40667255, 2025). "Specifically, FGFR2 has been identified as a driver of M2 macrophage polarization in colorectal cancer by increasing PAI-1 expression via the JAK2/STAT3 pathway." (PMID 39436561, 2024). "It was demonstrated that FGF7 interacts with FGF receptor 2 (FGFR2) and promotes tumour cell invasion in colorectal cancer." (PMID 38778448, 2024). "Reportedly, FGFR2 contributes to activating the JAK2/STAT3 pathway in colorectal cancer, resulting in the promotion of PD-L1 expression." (PMID 38326861, 2024). "FGFR2 has been reported to mediate immune tolerance in colorectal cancer cells by inducing PD‐L1 expression through the JAK/STAT3 pathway." (PMID 37750089, 2023). "The role of FGFR2 in ESCs is similar to its role in other cancer cell lines, including gastric, thyroid, and colorectal cancer cell lines." (PMID 35311468, 2022). "In our previous work, we demonstrated that snoRD126 promotes the progression of hepatocellular and colorectal cancer by upregulating FGFR2 to activate the PI3K-AKT pathway." (PMID 33891563, 2021). "For example, increased FGFR2 and FGFR4 expression were associated with poor response to neoadjuvant chemoradiation in colorectal cancer patients." (PMID 31948066, 2020). "In our study, we demonstrated that regorafenib effectively inhibits FGFR signaling and exerts antitumor activity in FGFR2‐amplified gastric and colorectal cancer cell lines." (PMID 29573334, 2018). "Here, we describe a novel FGFR2 amplification identified by clinical next-generation sequencing in a primary colorectal cancer." (PMID 28835367, 2017). "FGFR2 has been found to be highly expressed in colorectal cancer and correlated with tumor growth, invasion, and angiogenesis, and stronger FGFR2 expression has been observed in the invasive front of colorectal cancer cells." (PMID 27154171, 2016). "Up-regulation of C1GALT1 enhanced malignant phenotypes in colorectal cancer and hepatocellular carcinoma through FGFR2 and MET signaling pathways, respectively." (PMID 25762620, 2015). "We recently reported that C1GALT1 alters O-glycan structures on MET and enhances MET dimerization in hepatocellular carcinoma; and C1GALT1 modifies O-glycans on FGFR2 and its downstream signaling involved in colorectal cancer malignant phenotypes." (PMID 25762620, 2015). "Here we define a novel FGFR2 amplification in the NCI-H716 colorectal cancer cell line that was derived from the ascites of a poorly differentiated colon adenocarcinoma." (PMID 24968263, 2014). "Among them, FGFR2 and its isoform are highly expressed in colorectal cancer and correlate with tumor growth, metastasis, and angiogenesis." (PMID 24758762, 2014). "The co-expression of EGFR and FGFR2 linked to resistance to EGFR kinase inhibitors in esophageal cancer was reported, while the co-expression of EGFR and EPHA2 was found associated with the promotion of tumorigenesis in lung and colorectal cancer." (PMID 38338684, 2024). "Later, a correlation between FGFR2 and PD-L1 was found in colorectal cancer." (PMID 34503236, 2021).
colorectal cancer (continued). "Regorafenib effectively abrogates activated FGFR2 signaling in FGFR2‐amplified gastric and colorectal cancer and, therefore, might be considered for integration into treatment in patients with FGFR2‐amplified gastric and colorectal cancers." (PMID 29573334, 2018). "Genetic alternations in FGFR2 have been found to be associated with cancers other than breast but we have not found any association of FGFR2 SNPs with colorectal cancer in the published literature." (PMID 29698419, 2018). "In addition, among the four FGFRs (FGFR1-4), the significance of FGFR2 in colorectal cancer has been clearly demonstrated." (PMID 24758762, 2014). "Although FGFR2 amplification and overexpression are rare in colorectal cancer, our in vitro and in vivo models suggest that emerging FGFR inhibitors could have efficacy in a subset of colorectal cancer harboring this amplification." (PMID 24968263, 2014). "Several lines of evidence showed the effectiveness of targeting FGFR2 in colorectal cancer." (PMID 24758762, 2014). "This enzyme’s overexpression alters O-glycans on Fibroblast Growth Factor Receptor 2 (FGFR2), a receptor tyrosine kinase overexpressed in colorectal cancer." (PMID 38699634, 2024). "Less is known about the expression status of FGFR2 in GC or about HER2 and FGFR2 in other gastrointestinal cancers, such as colorectal cancer (CRC)." (PMID 35585358, 2022). "Finally, because the NCI-H716 cell line was derived from an ascites, and has features of endocrine differentiation, it remains possible that FGFR2 overexpression or gene amplification may be present at a higher frequency in colorectal cancers with these histological features." (PMID 24968263, 2014). "In concordance with these findings, 40% of colorectal cancers have mutant K-ras and therefore oncogenic signals might alter FGFR1 and FGFR2 activities to enhance immunosuppression." (PMID 34503236, 2021). "High expression and activation of FGFR2 was observed in NCI-H716 colorectal cancer cells, and FGFR2-selective small molecule inhibitors or FGFR2-specific shRNA strongly inhibited cell viability in vitro, indicating addiction of NCI-H716 cells to FGFR2." (PMID 29420662, 2018). "In other types of gastrointestinal cancers including colorectal cancers, hepatocellular carcinoma, and pancreatobiliary cancers, FGFR2 amplification is not frequently demonstrated." (PMID 29573334, 2018). "Although FGFR2 amplification is not common in primary colon cancer or lymph node and liver metastases, other subsets of colorectal cancer such as ascites, from which the NCI-H716 cell line was derived, have yet to be tested." (PMID 24968263, 2014). "Our results suggest that FGFR2 amplification is not widespread in common types of colorectal cancer or lymph node and liver metastases." (PMID 24968263, 2014). "We conclude that elevated FGFR2 expression but not amplification can be found in a small subset of colorectal cancers." (PMID 24968263, 2014). "FGFR2 was identified as a CAN gene by combined genomic studies in breast and colorectal cancers." (PMID 21108794, 2010). "Interestingly, FGFR2, its downstream receptor, was reported down regulated in colorectal cancer tissue compared to controls, but not in distant sites, suggesting a role of FGF7 within the peritumour microenvironment." (PMID 33670920, 2021). "Finally, pemigatinib did not result in MYC ecDNA loss in the COLO 320DM colorectal cancer cell line, which does not contain FGFR2 ecDNAs, showing that the loss of MYC ecDNAs in SNU16m1 cells is specifically due to the coupling with FGFR2 ecDNAs." (PMID 39506152, 2024). "NCI-H716 colorectal cancer cell line was included as a control, harboring an amplified full length FGFR2 kinase, whose hyper-activation is due to gene amplification and not to the presence of a concomitant fusion at the FGFR2 C-terminal with COL14A1 gene, conserving an intact kinase sequence." (PMID 31014245, 2019).
colorectal cancer (continued). "In the present study, we specifically focused on FGFR2 protein overexpression, particularly in the NCI-H716 colorectal cancer cell line, as determined by Western blotting, without direct assessment of gene amplification." (PMID 40871637, 2025). "We then compared FGFR2 expression and activation in NCI-H716 cells relative to a panel of nine colorectal cancer cell lines without FGFR2 amplification, and we found striking FGFR2 overexpression and phosphorylation only in NCI-H716 cells." (PMID 24968263, 2014).